BCL6 (BCL6 transcription repressor)
Diseases named in the same sentence as BCL6 in open-access papers (continued):
Sharing a sentence is not in itself a finding about the gene and the disease.
acute lymphoblastic leukemia (12 papers, 2013 to 2025). Leukemia with an acute onset, characterized by the presence of lymphoblasts in the bone marrow and the peripheral blood. "Our results were conceptually in line with recent findings showing that BCL6 enabled tumor cell tolerance to cytotoxic stress and conferred tyrosine kinase inhibitor resistance in Ph+ acute lymphoblastic leukemia." (PMID 35503721, 2022). "B-Cell CLL/Lymphoma 6 (BCL6) is a proto-oncogene that is highly expressed in acute lymphoblastic leukemia (ALL)." (PMID 28030830, 2017). "In response to TKI-treatment, BCL6 protein level was upregulated by 90 folds in BCR-ABL-positive acute lymphoblastic leukemia cells." (PMID 24252550, 2013). "Interestingly, the ratio of BACH2:BCL6 expression levels represent a significant predictor of outcome in acute lymphoblastic leukaemia (ALL)." (PMID 35008187, 2021). "For example, BCL6 is highly expressed in B cell acute lymphoblastic leukemia (ALL) mediated by pre-BCR signaling and Ikaros." (PMID 39456751, 2024). "PTEN was reported to be enriched in BCL6 promoter binding peaks of primary germinal center B cells, and BCL6 bound to the promoter locus of PTEN in lymphoblastic leukemia." (PMID 35503721, 2022). "Ph+ acute lymphoblastic leukemia (ALL) cells and IM-resistant chronic myeloid leukemia (CML) cells showed high expression of Bcl-6 protein." (PMID 28410239, 2017). "Homoharringtonine (HHT) exerts apoptotic effects against acute lymphoblastic leukemia (ALL) cells and chronic myeloid leukemia (CML) cells by decreasing expression of B cell lymphoma-6 (Bcl-6)." (PMID 32733254, 2020).
Autoimmunity (12 papers, 2017 to 2025). The occurrence of an immune reaction against the organism's own cells or tissues. "In fact, many genetic variants implicated in autoimmunity exhibit their greatest regulatory potential in GC-associated cellular populations, including BCL6 and transcription factors regulating B cell differentiation, such as POU domain class 2 homeobox associating factor 1 (POU2AF1) and HHEX." (PMID 35887298, 2022). "Subsequent research showed that BCL6 inhibition is also able to reduce germinal center formation in the setting of autoimmunity and infection." (PMID 41246349, 2025). "Our findings support BCL6 inhibition as a promising T1D immunotherapy, even after insulin autoimmunity is established in the B cell repertoire." (PMID 40909612, 2025). "Alternatively, BCL6 inhibitors have been utilized in suppressing the normal role of BCL6 in immunity, such as in the settings of immune rejection and autoimmunity." (PMID 39456751, 2024). "The implication of BCL-6 dependent pathways argues for occurrence of autoimmunity early within the process of sJIA chronification." (PMID 29848367, 2018). "A potent and cell-permeable BCL6 inhibitor with appropriate PK properties could, therefore, have clinical utility in suppressing antibody responses in autoimmunity." (PMID 34274316, 2021). "Therefore, the scope of BCL6 inhibition research has expanded to suppressing immune responses driven by BCL6-expressing B cells and Tfh cells, including its application in infectious diseases and autoimmunity." (PMID 41246349, 2025). "At approximately 1 year of age, CD4-ERα KO mice spontaneously showed mild autoimmunity with increased autoantibody production and CD4+CD44+CXCR5+Bcl-6+ TFH cells in the mesenteric lymph nodes and spleen." (PMID 30988419, 2019). "BCL6 was also directly upregulated on the array, which supports the hypothesis that this TF is of major importance (fold change 5.15, p = 0.002), and would also argue for even earlier involvement of autoimmunity with B cell responses in the course of the disease." (PMID 29848367, 2018). "The regulatory mechanism that BCL6 could be transactivated by STAT1 was also observed in imatinib-treated chronic myeloid leukemia cells and contributed to CD4+ T follicular helper cell TFH differentiation and autoimmunity." (PMID 35503721, 2022).
gastric cancer (12 papers, 2009 to 2023). A primary or metastatic malignant neoplasm involving the stomach. "BCL-6 also is associated with gastric carcinoma cell proliferation and invasion." (PMID 33376737, 2020). "Applying the BioTarget tool to BCL6, a TF associated with germinal center lymphocytes, we observed that patients with an active BCL6 pathway had significantly improved survival for breast, colon, and stomach cancer." (PMID 31227749, 2019). "BCL6 degradation caused by the HB-EGF-CTF also might induce cyclin D2 expression in human gastric cancers." (PMID 19337254, 2009). "BCL6 expression is also associated with differentiated gastric cancers." (PMID 19337254, 2009). "On the basis of these results, we speculate that in undifferentiated gastric cancers, the degradation of BCL6 induces cell-cycle acceleration through cyclin D2 expression and that this cell-cycle acceleration might be associated with undifferentiated gastric cancers." (PMID 19337254, 2009). "In this research, we aimed to explore the role and mechanism of BCL6 in malignant progression and ferroptosis of gastric cancer." (PMID 37060074, 2023). "In this study, we identified BCL6 as an important transcription repressor that inhibited the malignant progression and facilitates ferroptosis of gastric cancer." (PMID 37060074, 2023). "The overexpressed BCL-6 in gastric carcinoma tissues was positively correlated with a malignant phenotype in patients with gastric carcinoma." (PMID 33376737, 2020). "Taken together, data from our study suggest that PKM2 knockdown impeded cell migration, invasion, and EMT of gastric carcinoma cells via the HIF-1α/BCL-6 pathway." (PMID 33376737, 2020). "We thus assayed the expression levels of HIF-1α and BCL-6 in gastric carcinoma cells transfected with PKM2 siRNA." (PMID 33376737, 2020). "Mutation analysis using public database showed that BCL6 is mostly amplified, whereas deletion or mutation of ZBTB28 was detected in lung, head and neck squamous (HNSCC), ESCC and gastric carcinomas." (PMID 31754389, 2019). "It has been reported that miR-127 is significantly reduced in gastric cancer tissues and osteosarcoma cell lines and that BCL6 is overexpressed in invasive breast cancers." (PMID 24282530, 2013). "In the HB-EGF-positive group of human gastric cancer samples, BCL6 expression is also inversely correlated with cyclin D2 expression." (PMID 19337254, 2009). "Cytoplasmic translocated BCL6 was degraded by the ubiquitin/proteasome pathway, and the degradation of BCL6 induced cyclin D2 expression in gastric cancer cell lines that expressed endogenous BCL6, HB-EGF-CTF, and cyclin D2." (PMID 19337254, 2009). "We found that BCL6 expression is closely linked with the downregulation of cyclin D2, as determined by immunohistochemistry, in cases of HB-EGF-positive human gastric cancer." (PMID 19337254, 2009). "Inhibition of HB-EGF-CTF nuclear translocation and maintenance of BCL6 function are important factors in the regulation of gastric cancer progression." (PMID 19337254, 2009). "In the process of gastric cancer progression, BCL6 is decreased by HB-EGF-CTF signalling and the ubiquitin/proteasome pathway." (PMID 19337254, 2009). "In conclusion, this is the first report to investigate the transcriptional repressor BCL6 in gastric cancers." (PMID 19337254, 2009). "Of the 100 cases of gastric cancer, 24 were BCL6 positive (positive rate=24%) and 76 cases were BCL6 negative." (PMID 19337254, 2009). "Inhibition of HB-EGF-CTF nuclear translocation and maintenance of BCL6 function are important for the regulation of gastric cancer progression." (PMID 19337254, 2009). "We also identified a link between the expression of BCL6 (determined by immunohistochemistry) and the histological type of human gastric cancers." (PMID 19337254, 2009).
gastric cancer (continued). "Considering these facts, our data indicate that HB-EGF-CTF nuclear translocation caused the degradation of BCL6 and that this degradation reverses cyclin D2 repression in gastric cancer cell lines that express endogenous BCL6, HB-EGF-CTF, and cyclin D2." (PMID 19337254, 2009). "In addition, PKM2 was reported to promote migration, invasion, and EMT of gastric carcinoma by HIF‐1α/BCL‐6 Pathway." (PMID 34898024, 2022). "Similarly, BCL-6 overexpression restored the downregulated expression of BCL-6 in gastric carcinoma cells (p < 0.05)." (PMID 33376737, 2020). "However, HIF-1α overexpression restored the downregulated expression of BCL-6 in gastric carcinoma cells (p < 0.05)." (PMID 33376737, 2020). "In gastric carcinoma cell lines, BCL-6 was also upregulated." (PMID 33376737, 2020). "The mechanism that BCL6 regulate transcription of cyclin D2 might also happen in gastric cancer cells." (PMID 19337254, 2009). "Thus, we found that BCL6 expression correlated with the downregulation of cyclin D2 expression in human gastric cancer tissues that are HB-EGF positive." (PMID 19337254, 2009). "This interaction causes nuclear export and degradation of BCL6 and might result in the downregulation of BCL6 repressor activity for the cyclin D2 promoter in gastric cancer cells." (PMID 19337254, 2009). "Our present data reveal that BCL6 expression is reduced in undifferentiated gastric cancers." (PMID 19337254, 2009). "In the present study, we investigated the BCL6 function in gastric cancers." (PMID 19337254, 2009). "BCL6 expression levels in differentiated and undifferentiated gastric cancers may provide further evidence in gastric cancer progression." (PMID 19337254, 2009). "We also performed BCL6 immunohistochemistry on specimens of human gastric cancers." (PMID 19337254, 2009). "In addition, the expression and function of BCL6 in gastric cancer could be strengthened by the RNF180/RhoC pathway." (PMID 37060074, 2023). "Moreover, downstream transcription factors, such as c-myb, cyclinB1/G2, and BCL-6 might be involved in AK023391-induced tumorigenesis in gastric cancer." (PMID 29282102, 2017). "Our results showed that CLDN10 expression significantly correlated to the expression of B cells (CD19, CD79A) and Tfh cells (BCL6, IL21) markers, which indicated a potential mechanism for CLDN10 to regulate B cell function in gastric cancer." (PMID 34721537, 2021). "BCL-6 inhibition by miR-519d-3p suppressed cell proliferation, invasion, cell cycle, and EMT in gastric carcinoma cells." (PMID 33376737, 2020). "We also immunohistochemically studied 100 surgical specimens of advanced gastric cancers to analyse the expression of HB-EGF, BCL6, and cyclin D2." (PMID 19337254, 2009). "The inverse correlation between BCL6 and cyclin D2 was also found in HB-EGF-positive human gastric cancers." (PMID 19337254, 2009). "In the present study, our immunohistochemical analysis revealed an inverse correlation between BCL6 and cyclin D2 expression in the group of HB-EGF-positive human gastric cancers." (PMID 19337254, 2009). "In the present study, we investigated the interaction of BCL6 with HB-EGF-CTF and the mechanism of cyclin D2 expression by this interaction in gastric cancer cell lines, which express endogenous HB-EGF, BCL6, and cyclin D2." (PMID 19337254, 2009). "In gastric carcinoma, BCL-6 was overexpressed in human gastric carcinoma tissues compared with adjacent nontumor tissues." (PMID 33376737, 2020). "Our data indicate that BCL6 interacts with HB-EGF-CTF and that this interaction might induce the cyclin D2 expression in human gastric cancer." (PMID 19337254, 2009). "There have been no previous reports of the relationship between BCL6 and gastric cancer histological type." (PMID 19337254, 2009). "We performed immunohistochemical analyses of BCL6, HB-EGF and cyclin D2 in human gastric cancers." (PMID 19337254, 2009).
gastric cancer (continued). "BCL6 is a transcriptional repressor that has important functions in lymphocyte differentiation and lymphomagenesis, but there have been no reports of BCL6 expression in gastric cancers." (PMID 19337254, 2009). "In the present study, BCL-6 overexpression reversed the effect of PKM2 knockdown on the invasion, migration, and EMT in gastric carcinoma cell, suggesting that BCL-6 might play a fundamental role in the function of PKM2 silencing in gastric carcinoma cell invasion, migration, and EMT." (PMID 33376737, 2020). "However, to our knowledge, there have been no reports of BCL6 in gastric cancer." (PMID 19337254, 2009).
myeloma (12 papers, 2011 to 2025). "Genes frequently mutated in DLBCL, FL and/or multiple myelomas (MM) such as BCL6 and BCL2 are found in or near spot K upregulated in healthy B cells and, to a lesser degree, in FL, and downregulated in BL and DLBCL." (PMID 31039827, 2019). "Spot H shows prominent expression also in multiple myelomas (MM) accompanied by deactivation of BCL6-related transcriptional programs (spot K) as a hallmark of plasma cell maturation which is further paralleled by high expression of spot L reflecting B cell-like characteristics." (PMID 31039827, 2019). "FICTION is a powerful technique, which has been used extensively in haematopoietic malignancies, e.g. to identify BCL6 imbalances in nodular lymphocyte predominant Hodgkin lymphoma or 14q32 chromosomal rearrangements in multiple myeloma." (PMID 29720207, 2018). "Although evidence for BCL6 expression in primary myeloma is limited, some evidence of expression has been observed." (PMID 24385976, 2013). "In addition, persistent IL-6/STAT3 signaling can aberrantly reactivate BCL6 expression in IL-6–dependent myeloma cells, fostering uncontrolled proliferation and treatment resistance." (PMID 41357603, 2025). "Bcl-6 was also upregulated in myeloma-switched memory B cells." (PMID 36752202, 2023). "Interestingly, in a myeloma cell line model co-expression of BCL6 and MTA3 can drive a phenotypic reversion with B-cell antigen expression." (PMID 24385976, 2013). "In fact, it has been previously reported that the interaction of myeloma cells with different types of cells of the bone marrow microenvironment promotes a reduction of CD138 expression, a less differentiated morphology and an increase of the B-cell associated transcription factor, Bcl6." (PMID 24658332, 2014). "While BCL6 expression and phenotypic reversion may provide an explanation for observations in advanced myeloma, and myeloma cell lines, it is important to distinguish between such transformed states and those operating in normal plasma cells, and early plasma cell neoplasms." (PMID 24385976, 2013). "Then spleen cells from the mouse, which has high titer of antiserum against BCL6, were isolated and fused to SP2/0 myeloma cells." (PMID 31063496, 2019). "BCL6 expression can be stimulated by cytokines such as IFN-γ, IL-6, type I IFN, IL-12, and TNF-α in myeloma or TFH cells." (PMID 30687256, 2018). "DEPTOR knockdown in H929 and MM1S cell lines induced dedifferentiation of myeloma cells, as demonstrated by the upregulation of PAX5 and BCL6, the downregulation of IRF4, and a clear reduction in cell size and endoplasmic reticulum mass." (PMID 28420429, 2017).
chronic myeloid leukemia (11 papers, 2017 to 2025). "The dependence of BCL6 expression on STAT1 has been observed in imatinib-treated chronic myeloid leukemia cells." (PMID 36377663, 2022). "It was reported that BCL6 is associated with tyrosine kinase inhibitors (TKI) resistance in Philadelphia chromosome positive (Ph+) ALL and chronic myeloid leukemia (CML) cells." (PMID 33629212, 2021).
malaria (10 papers, 2016 to 2025). Malaria is a serious and sometimes fatal disease caused by a parasite that commonly infects a certain type of mosquito which feeds on humans. "Moreover, this study showed that PfGARP triggered Bcl6 expression across cTFH subsets, whereas PfSEA-1A induced more cMAF expression, demonstrating the feasibility of implementing T-cell immune correlates to down-select new malaria candidates." (PMID 40402846, 2025). "In favor of this, a lower expression of CXCR3 along with an augmented BCL6 and PD-1 expression in the present study, possibly suggest the increased population of TFH cell following malaria pathology." (PMID 31614626, 2019). "P2RX7 acts at the beginning of the malaria immune response, before Th1/Tfh polarization, when activated CD4+ T cells constitute a single population that co-expresses T-bet and Bcl6, and contributes exclusively to the differentiation of Th1 cells, without affecting the generation of early Tfh cells." (PMID 36993971, 2023). "Here, we characterize Bcl-6/Bcl-xL B cell immortalization across multiple tissue types and B cell subsets in healthy and HIV-1 infected individuals, as well as individuals recovering from malaria." (PMID 36582240, 2022). "Indeed, others have suggested that the Th1 and Tfh cells can exist as a continuum, where the balance between Bcl6, STAT3, Blimp-1 and Tbet expression in CD4+ T cells determine the predominant Th subset in effector CD4+ T cells in malaria." (PMID 36845571, 2021). "GC-TFH cells are essential for host survival during experimental malaria and their development proceeds via a step-wise process involving upregulation of PD-1, CXCR5, and Bcl6 expression that culminates with the localization of GC-TFH cells in the germinal center." (PMID 33529242, 2021). "BCL6 (B cell CLL/Lymphoma 6) expression level was also found elevated in the SM group which suggest suppression of macrophage cells proliferation and inhibition of Th1-Th2 cells differentiation in response to malaria severity." (PMID 31614626, 2019). "We, therefore, examined the signature genes associated with cluster 10 and found enrichment of the transcription factor TCF1 (gene name Tcf7); this has been associated with circulating TFH cells in a mouse model of malaria, but we found no significant enrichment for PD1, CXCR5, or BCL6." (PMID 40214640, 2025). "A more recent report using a mouse model of malaria demonstrated that therapeutic release from PD-1 exhaustion, coupled with stimulation via OX40 dramatically increased IFNγ production by Th1 cells, which destabilized Bcl-6 in established Tfh cells and resulted in defective humoral immune responses." (PMID 27812214, 2016).
non-small cell lung carcinoma (10 papers, 2018 to 2025). A group of at least three distinct histological types of lung cancer, including non-small cell squamous cell carcinoma, adenocarcinoma, and large cell carcinoma. "Specifically, the BCL6 gene, as one of the off-target, has been implicated in a variety of tumors, such as B-acute lymphoblastic leukemia and non-small cell lung cancer." (PMID 34133740, 2021).